IL18 (interleukin 18)
Diseases named in the same sentence as IL18 in open-access papers (continued):
Sharing a sentence is not in itself a finding about the gene and the disease.
atherosclerosis (continued). "As the adaptive immune system is involved in the development of atherosclerosis, the importance of IL-18 is considered crucial, especially when we focus on CKD-related atherosclerosis and its clinically relevant consequences." (PMID 35204237, 2022). "Hence, whether targeting IL-6, downstream of IL-1 and IL-18, might quell inflammation with less impairment of host defenses, especially since IL-6 is causally involved in atherosclerosis, as shown by Mendelian randomization analysis, is an ongoing issue that warrants further investigation." (PMID 36082127, 2022). "(iv) AIM2 inflammasome activation and atherogenic proinflammatory factor interleukin-1β (IL-1β) and interleukin-18 (IL-18) release promote inflammatory responses of atherosclerosis." (PMID 35646157, 2022). "It should be noted that NLRP3-dependent activation of IL-18 production is involved not only in the pathogenesis of AD and atherosclerosis." (PMID 36138973, 2022). "For our analysis, we chose three cytokines that lead in the processes of atherosclerosis: interleukin 6 (IL-6), interleukin 18 (IL-18) and tumor necrosis factor α (TNF-α)." (PMID 35630041, 2022). "Among the cytokines IL-17, IL-18 and IL-1β, IL-18 has been reported to be potent in inducing and sustaining inflammatory diseases including atherosclerosis." (PMID 35531433, 2022). "The main pathways and biological processes involved are lipids and atherosclerosis, IL-18 signaling pathway, TWEAK signaling pathway, response to oxidative stress, hematopoietic function, and negative regulation of cell differentiation." (PMID 36482625, 2022). "IL-1β and IL-18 are considered to be the two most prominent inflammatory cytokines in the inflammasome that promote the development of atherosclerosis." (PMID 36589841, 2022). "LDL-c induces activation of inflammasome, leading to the production of IL-1β and IL-18, which in turn accelerate atherosclerosis." (PMID 36231033, 2022). "Multiple studies have shown that NLRP3 inflammasome, IL-1β, IL-18 and pyroptosis have a decisive and important role in various diseases, such as DM, atherosclerosis, and Alzheimer’s disease." (PMID 35844498, 2022). "In people with coronary artery disease, variations in the IL18 gene consistently affect circulating levels of IL-18 and clinical outcomes, supporting the idea that IL-18 contributes to atherosclerosis and its consequences." (PMID 36499335, 2022). "There are some data from ex vivo investigations and a knockout mice study showing that both IL-18 and IL-17 are involved in the development of inflammation, suggesting the synergistic role of IL-18 and IL-17 in the development of atherosclerosis." (PMID 35160217, 2022). "The significantly activated biological pathways were NAFLD, fluid shear stress and atherosclerosis, and interleukin-18 signaling pathway." (PMID 36003913, 2022). "Combining several clinical studies, we propose that IL-18 not only accelerates the progression of atherosclerosis in CKD patients but also has a predictive value for cardiovascular prognosis in CKD patients." (PMID 35222026, 2022). "Previous studies have confirmed that atherosclerosis is mainly attributed to inflammation and the products of pyroptosis such as IL-1β, IL-18, IL-1α, ATP, and GSDMD-N, suggesting crucial role of pyroptosis in the pathogenesis of atherosclerosis." (PMID 36304814, 2022). "The arterial tissue from patients with atherosclerosis showed an increased expression of IL-18 and its receptor compared with healthy tissue." (PMID 35204152, 2022). "In recent years, interleukin-1β (IL-1β) and interleukin-18 (IL-18) have been identified as the two most important inflammatory cytokines that promote the development of atherosclerosis." (PMID 36589841, 2022).
atherosclerosis (continued). "It has also been shown that TREM-1 apparently mediates ox-LDL-induced endothelial cell pyroptosis, a cell death process found in atherosclerosis, which is dependent on caspase-1 activation and IL-1β and IL-18 production." (PMID 33814983, 2021). "Inflammatory cytokines, particularly IL-1β and IL-18, play varying roles in the development of atherosclerosis." (PMID 32378144, 2021). "IL18 has also been reported to be involved in abdominal aortic aneurysm formation and atherosclerosis." (PMID 35069552, 2021). "In the context of atherosclerosis, IL-18 expression is predominantly detected in macrophages, while IL-18R is expressed on endothelial cells (ECs), smooth muscle cells (SMCs), lymphocytes and macrophages." (PMID 33562334, 2021). "A thin fibrous cap in the lesion, which is indicative of unstable plaques prone to rupture and increased atherosclerosis correlate with increased Th17 cells, IL-23-producing vascular muscle, and macrophages in apoE/IL18 double-KO mice." (PMID 35087531, 2021). "IL-1β and IL-18 are two key in?ammatory factors in atherosclerosis development and are mainly regulated by the NLRP3 inflammasome." (PMID 34094640, 2021). "Together, these results link IL-18-mediated downregulation of TRAIL (an atherosclerosis-promoting mechanism) with upregulated IL-32 expression and suggest an upstream regulatory role for IL-32 in this process." (PMID 33936102, 2021). "By contrast, the genetic deletion of IL-1β and IL-18 significantly reduced the development of atherosclerosis in ApoE-/- mice." (PMID 34094640, 2021). "Subsequently, active caspase-1 leads to proteolytic cleavage of pro-inflammatory cytokines such as pro-IL-1β and pro-IL-18 into their mature and active forms, which are the most important cytokines involved in the progression of atherosclerosis." (PMID 32378144, 2021). "Mouse studies were used to investigate the effects of the NLRP3 inflammasome’s downstream cytokines, IL-1β, and IL-18 on atherosclerosis in the early 2000s." (PMID 32648087, 2021). "IL-1β and IL-18 are produced in response to inflammasome activation and play essential roles in the initiation and progression of atherosclerosis." (PMID 33534121, 2021). "Arglabin, a plant-derived compound, inhibited the activity of the NLRP3 inflammasome and significantly reduced the production of IL-1α, IL-1β, and IL-18, reducing the production of proinflammatory mediators to alleviate atherosclerosis." (PMID 32328119, 2020). "Since P2X7 expressed by human macrophages is also involved in ATP stimulated IL-18 release it again represents a suitable candidate for pharmacological targeting of atherosclerosis." (PMID 33664731, 2020). "Here, we presented the stochastic Petri net model of the involvement of IL-18 in the atherosclerosis process." (PMID 33202974, 2020). "A previous study has demonstrated that IL-18 was a potential predictive marker for atherosclerosis progression in SIV-infected rhesus monkeys (Macaca mulatta) on a high-fat/high-cholesterol diet." (PMID 32676215, 2020). "The results of our research show beyond any doubt that in atherosclerosis, being immuno-inflammatory disorder, IL-18 and INF-γ play a key role." (PMID 33202974, 2020). "The receptor is also endowed with the ability to induce transcription and secretion of inflammatory cytokines such as IL-1β, IL-18 (topic 5) and IL-6 which are central in atherosclerosis." (PMID 33664731, 2020). "IL-18 is involved in the progression of sterile inflammatory diseases including atherosclerosis, metabolic and neuro-inflammatory disorders." (PMID 33101286, 2020). "Our motivation for this research was to investigate the complex interactions that affect interleukin 18 (IL-18) as well as the effects of the cytokine itself on related pathways in atherosclerosis." (PMID 33202974, 2020).
atherosclerosis (continued). "IL-1α, IL-1β, and IL-18 are proinflammatory molecules involved in atherosclerosis disease progression, while the anti-inflammatory cytokines TGF-β, IL-33, IL-10, and IL-13 function in the reduction of atherogenesis in cardiovascular disorders." (PMID 32676215, 2020). "The NLRP3 inflammasome is clearly involved in the pathogenesis of diabetes, atherosclerosis, and infectious disease due to the secretion of IL-1β and IL-18 from this complex." (PMID 30616678, 2019). "In diabetic ApoE−/− mice model, cPKCβ can damage vascular endothelial cells through the IL-18/IL-18 binding protein pathway, promote the formation of atherosclerosis, and cPKCβ inhibitor can relieve the progression of atherosclerosis." (PMID 31521120, 2019). "As shown, LDL-C induces inflammasome activation, leading to the production of IL-1β and IL-18, which accelerate atherosclerosis." (PMID 31672136, 2019). "IL-18 belongs to the IL-1 superfamily, which plays an important role in inflammatory cascade and atherosclerosis." (PMID 30906223, 2019). "Atherosclerosis in ApoE−/− mice is also reduced and plaques are stabilized by IL-18 blockade with an IL-18 binding protein or by genetic deletion." (PMID 31653058, 2019). "Recent studies have shown that the NLRP3 inflammasome and IL-1β/IL-18 play important roles in gout, rheumatoid arthritis, atherosclerosis, DM, and oxalate-related nephropathy diseases." (PMID 29929501, 2018). "Some studies have reported the presence of serum IL-18 levels, IL-18 gene variants, and mRNA levels in AMI, CAD, stroke, and atherosclerosis." (PMID 29485097, 2018). "Upregulation of IL-10 expression with a concomitant decrease in the production of TNF-α and IL-18 was put forward as a direct anti-inflammatory mechanism of IL-37 mediated amelioration of atherosclerosis and CAC." (PMID 29641433, 2018). "Atherosclerosis is a chronic inflammatory disease that is promoted, among others, by pro-inflammatory cytokines such as IL-1β and IL-18 produced by NLRP 3 inflammasome." (PMID 28950870, 2017). "We elected to focus on IL‐18, IL‐33, and TNF, because these cytokines have been implicated in the pathology of both atherosclerosis and RA." (PMID 26749303, 2016). "Among other cytokines, IL-1β and IL‐18 are known to be an important modulators in artery wall inflammation and acceleration of atherosclerosis." (PMID 26523150, 2015). "The analysis of the model indicated that IL-18, due to its pleiotropic properties, is essential for many signaling pathways, what makes it an important player in atherosclerosis process and very attractive target for researchers." (PMID 26669254, 2015). "IL-27 is a member of the IL-12 family of cytokines that, in contrast to IL-12 and IL-18, limits the intensity and duration of T cell responses, and limits atherosclerosis in animal models of atherosclerosis." (PMID 25699211, 2015). "Cytokines such as IL-1β, IL-18, IL-6 and TNF-α are key mediators in chronic vascular inflammatory response underlying several aspects of atherosclerosis and cardiovascular disease." (PMID 26600018, 2015). "It is notable that IL-1β, IL-18, TNF-α, and IFN-γ play critical pathogenic roles in atherosclerosis, and increased levels of these cytokines are associated with the onset of ACS." (PMID 24733959, 2014). "IL-18, an NF-κB-activated proinflammatory cytokine, has been demonstrated to promote the development of atherosclerosis." (PMID 23741427, 2013). "Increasing evidence from both experimental and clinical studies indicates that IL-18 is a key player in the inflammatory process leading to atherosclerosis." (PMID 24040261, 2013).
atherosclerosis (continued). "With the knowledge that atherosclerosis is influenced by an inflammatory process, IL-18 is one of the inflammatory biomarkers that lately has been in focus amongst researchers in cardiovascular disease (CVD)." (PMID 22141572, 2011). "Both IL1 and IL18 signal through MyD88, and their absence in experimental mouse atherosclerosis also has the effect of limiting atherosclerosis development." (PMID 21526997, 2011). "IL-18 is implicated in the pathogenesis of several diseases including atherosclerosis and ischemic heart disease, and more recently a novel function for IL-18 in the control of energy homeostasis has also been described." (PMID 20169140, 2010). "Animal models have also provided evidence that the pro-inflammatory cytokine interleukin 18 (IL-18) contributes to the development of atherosclerosis." (PMID 19347053, 2009). "The study of one single cytokine role in atherosclerosis is extremely difficult, seeing that some of these biomarkers induce the activity of others; for example, IL-1 induces IL-6, IL-18, and CRP, for which a combination of cytokines is possibly a better choice." (PMID 41226718, 2025). "ZL, in combination with atorvastatin, can inhibit the activation of the NF-κB/NLRP3 signaling pathway and limit the release of p-NF-κB, NLRP3, caspase-1, IL-1β, and IL-18, thereby alleviating vascular inflammation and significantly attenuating atherosclerosis in rabbits." (PMID 40373162, 2025). "IL-18, a proinflammatory cytokine from the superfamily of interleukin 1 (IL-1), which is responsible for regulating immune response, was also described as aggravating atherosclerosis." (PMID 40573228, 2025). "Moreover, the NLRP3 inflammasome, a complex comprising the NLRP3 receptor, ASC adapter, and pro-caspase-1, plays a pivotal role in atherosclerosis development by catalyzing the maturation of caspase-1, which in turn generates IL-1β/IL-18 from pro-IL-1β/IL-18." (PMID 38919547, 2024). "IL‐18, akin to IL‐1β, sparks inflammation in atherosclerosis and plaque instability." (PMID 38402570, 2024). "This is mediated largely by IL-1β and, in some diseases (atherosclerosis), additionally by IL-18." (PMID 37239938, 2023). "We then detected the levels of IL-1β and IL-18 in arteries with atherosclerosis." (PMID 37198205, 2023). "The study proposed that it could be feasible to control the development and adverse outcomes of atherosclerosis by regulating IL-18 signaling, such as through the use of antagonists of IL-18." (PMID 37637634, 2023). "CHI3L1, CD36, IL-18, and RARRES2 genes have also been reported to be associated with IR, whereas APOA1, CD36, LEP, FN1, and CETP genes were found to be associated with atherosclerosis." (PMID 36984867, 2023). "Interleukin-18 (IL-18) shows atherosclerosis-promoting effects in ECs." (PMID 37893187, 2023). "IL-18 modulates inflammation and plaque stability to promote atherosclerosis, but it is unclear whether IL-18 independently predicts atherosclerosis." (PMID 37822930, 2023). "The significant effect of IL-18 on atherosclerosis has been widely investigated." (PMID 37374202, 2023). "Both IL-1β and IL-18 play crucial roles in the development of atherosclerosis." (PMID 37374202, 2023). "We have identified seven genes (CHI3L1, CD36, LEPR, RETN, IL-18, RBP-4, and RARRES2) that may be associated with IR and atherosclerosis as having possible evidence based on the disease pathogenesis of ED and inflammation." (PMID 36984867, 2023). "There are also reports indicating that increased expression of IL-18 and IL-17 in arterial endothelium may lead to the rapid development of atherosclerosis." (PMID 35160217, 2022). "As an inflammasome of NLRP3, IL-18 can accelerate atherosclerosis in mice." (PMID 35785176, 2022). "Moreover, accumulating evidence has shown that NLRP3 activation products IL-1β and IL-18 both play an important role in the occurrence of atherosclerosis." (PMID 35844498, 2022).
atherosclerosis (continued). "It has been anteriorly described that the expression of IL-37 is involved in the pathogenesis of atherosclerosis and that this biomarker has an inflammatory effect by reducing the expression of other inflammatory cytokines, such as interleukin-18 (IL-18) and TNF-α." (PMID 36012430, 2022). "Inflammasomes in macrophages generate interleukin-1 (IL-1), interleukin-18 (IL-18), and other pro-inflammatory cytokines, which are chemotactic toward other inflammatory cells, including B-cells and T-cells, which are significant drivers of atherosclerosis." (PMID 36003909, 2022). "All these data strengthen the hypothesis that there is a connection between IL-18, systemic inflammation, dyslipidemia, and atherosclerosis in PsA." (PMID 35160217, 2022). "Moreover, IL-18 is expressed in human atheroma cells, such as vascular ECs, SMCs, and macrophages, and also participated in the development of atherosclerosis." (PMID 35464402, 2022). "Previous reports have shown that IL-18 may promote the progression of atherosclerosis, destabilize atherosclerotic plaque and accelerate plaque formation." (PMID 35630041, 2022). "Therefore, the NLRP3 inflammasome has attracted interest as a targetin atherosclerosis due to its ability to generate both active forms ofIL-1β and IL-18." (PMID 39077721, 2022). "In addition, administration of IL-18 by intraperitoneal injections into ApoE−/− mice aggravated atherosclerosis lesions." (PMID 35464402, 2022). "NLRP3 inflammasome and the downstream pro-inflammatory cytokines IL-1β and IL-18 are attractive pharmaceutical candidates for therapeutic intervention of atherosclerosis, and selectively neutralizing these cytokines has been shown to be available in the context." (PMID 35459215, 2022). "Moreover, we proved that IL-18 along with the directly dependent signaling pathways (IL-18-MyD88 axis) are crucial for atherosclerosis and can be considered as a good candidate for an atherosclerosis biomarker." (PMID 35204237, 2022). "A growing number of studies have demonstrated the critical role of IL-18 in atherosclerosis." (PMID 36589841, 2022). "IL-1β and IL-18 have important roles in the pathogenesis of atherosclerosis." (PMID 36589841, 2022). "Thus, the excessive release of IL-1β and IL-18 attributed to pyroptosis is one of the factors that aggravate atherosclerosis, but meanwhile, the over-inhibition of inflammation also leads to plaque instability." (PMID 35096837, 2021). "Furthermore, our in vitro functional data linked IL-32 to macrophage activation and production of IL-18 and downregulation of TRAIL, a mechanism previously shown to be associated with impaired cholesterol metabolism and atherosclerosis." (PMID 33936102, 2021). "Moreover, IL-18 is also important for quality control of microbiota and taming of inflammation-regulated metabolic diseases, all of which immensely impact atherosclerosis and whose modeling requires precise controls in long-term in vivo experiments." (PMID 33562334, 2021). "Activation of NLRP3 inflammasome and IL-1 cytokines such as IL-1β and IL-18 were shown to be critically involved in the ensuing post-infarct systemic inflammation and progression of atherosclerosis through contributing to the initiation, formation, growth, and rupture of atherosclerotic plaques." (PMID 33804661, 2021). "Additionally, NLRP3 inflammasome can promote the conversion of IL‐18 and IL‐1β precursors into mature IL‐18 and IL‐1β, which plays a key role in atherosclerosis." (PMID 34331512, 2021). "Strategies for inhibiting IL-18 have shown diminution in experimental atherosclerosis." (PMID 33924019, 2021).